IL10 (interleukin 10)
Diseases named in the same sentence as IL10 in open-access papers (continued):
Sharing a sentence is not in itself a finding about the gene and the disease.
hematological malignancies (continued). "Therefore, IL-10 CAR-T has potential applications in the treatment of a broad of hematological malignancies, not only AML." (PMID 34392305, 2021). "Finally, this analysis emphasizes the discrepant application of IL-10-targeted drugs toward solid tumors and hematological malignancies." (PMID 26440936, 2015). "Hematological disorders, such as hemoglobin concentration, negatively correlated with TNF-α, IL-6, IL-27 and IL-10 (all p ≤0.0005); Platelet and eosinophil counts were negatively correlated with TNF-α, IL-6, IL-27 and IL-10 (p ≤0.0005)." (PMID 26814478, 2016). "In conclusion, in patients with hematological malignancies who underwent cell therapies, the ability to acutely upregulate IFN-γ and IP-10/CXCL10 at the priming vaccination and IFN-γ, IL-15, IL-7 and IL-10 upon booster vaccination were predictive of successful Ab development." (PMID 35693807, 2022). "Moreover, unmutated IgHV CLL cells generally produce less IL-10, an immunosuppressant molecule, which may explain the exaggerated reactions and the higher incidence of EDHM among CLL patients compared to other hematologic malignancies." (PMID 37614953, 2023). "Concerning patients with hematological malignancies, a value of PCT ≥ 0.54 ng/mL has been demonstrated as accurate in differentiating children with or without bacteraemia alone or in combination with IL10." (PMID 41190512, 2025).
liver (23 papers, 2010 to 2025). "For example, SCFAs have been reported to exert inhibitory effects on the production of pro-inflammatory cytokines, enhance the expression of IL-10, activate regulatory T-cell (Tregs), in turn reduce colon inflammation." (PMID 38596637, 2024). "In this study, we found that PGE2 produced by hP-MSCs mediated the polarization of M2 macrophages, which produced IL-10 to possibly mediate the effect of colon inflammation attenuation." (PMID 32685014, 2020). "Also, IL-10 was significantly decreased with IFNγ or IL-17A treatments, suggesting a decrease in inhibitory factors concomitant with an increase in cytotoxicity in two GI tumor models." (PMID 33042110, 2020). "Gastrointestinal tumors often display a immunosuppressive cytokine profile with the TIME, characterized by factors like TGF-β, IL-10, and VEGF characterized by factors such as TGF-β, VEGF, and IL-10." (PMID 40917849, 2025). "In conclusion, we report previously unrecognized pro-tumorigenic roles for G-CSF in gastrointestinal tumors through inhibition of CD4+ and CD8+ T cell responses by promoting IL-10 and reducing cytotoxic responses in IFNγ- and IL-17A- dependent mechanisms." (PMID 33042110, 2020). "In summary, we report here previously unrecognized pro-tumorigenic roles for G-CSF in gastrointestinal tumors through inhibiting CD4+ and CD8+ T cell responses by promoting IL-10 secretion and reducing cytotoxic responses." (PMID 33042110, 2020). "However, in GI tumors, this function is frequently suppressed by the immunosuppressive milieu, which upregulates inhibitory ligands such as PD-L1 and HLA-E and secretes suppressive cytokines including TGF-β and IL-10." (PMID 40917849, 2025). "Peritoneal cavity-derived B cells, although naturally enriched for IL-10-producing cells, were solely able to ameliorate, but not to prevent, T cell-induced colon inflammation when transferred to Rag−/− recipients along with colitogenic CD4+CD25−CD45RBhi T cells." (PMID 27353032, 2016).
heart disease (21 papers, 2012 to 2024). "Anti-inflammatory cytokines, such as IL-10, also play a role in cardiac disease by modulating the deleterious effects of exacerbated inflammation." (PMID 38892020, 2024). "In heart disease, the administration of IL-10 was shown to result in a significant suppression of proinflammatory cytokine synthesis, MMP-9 activity, and the infiltration of inflammatory cells in the myocardium, leading to a reduction in cardiac fibrosis." (PMID 38792896, 2024). "In this review, the pathophysiological effects of interleukins including the IL-1 family (IL-1, IL-18, IL-33, and IL-37), IL-2, IL-4, the IL-6 family (IL-6 and IL-11), IL-8, IL-10, and IL-17 on primary cell types of heart disease is elucidated." (PMID 37047468, 2023). "Cardioprotective effects of IL-10 on the cardiomyocytes of heart diseases were found in a variety of previous studies." (PMID 37047468, 2023). "It has been shown that patients who present a mild heart disease or are in the indeterminate phase of CD produce high levels of IL-17 and IL-10 whereas patients with severe heart disease show high levels of IFN-γ and TNF-α." (PMID 35097133, 2022). "Several inflammatory cytokines, such as TNFα, the IL-1 family, IL-6, IL-8, IL-10, IL-18, and IFNα have also been shown to play a pathological role in various heart diseases." (PMID 35069538, 2021). "In conclusion, BA5 had a potent anti-inflammatory activity on a model of parasite-driven heart disease related to IL-10 production and a switch from M1 to M2 subset of macrophages." (PMID 31244833, 2019). "Both, CCL2 and IL-10, are potential indicators of cardiac tissue inflammation and heart disease in experimental models and human in the last decades." (PMID 28377930, 2017). "On the other hand, it is possible that IND patients who are able to always keep high levels of IL-10 secretion has less chance to develop cardiac disease." (PMID 22625224, 2012). "This review will primarily focus on the pathophysiological effects of various interleukins including the IL-1 family (IL-1, IL-18, IL-33, IL-37), IL-2, IL-4, the IL-6 family (IL-6 and IL-11), IL-8, IL-10, IL-17 on primary cells of heart disease-CMs, FBs, ECs, and immune cells." (PMID 37047468, 2023). "In addition, we found indications that they had above-median levels of the anti-inflammatory cytokine IL-10 and that they were less likely to have family histories of heart disease." (PMID 34518517, 2021). "Finally, we conclude that the betulinic acid derivative BA5 had a potent anti-inflammatory activity on a model of parasite-driven heart disease, being related to elevated IL-10 production and a switch from M1 to M2 macrophage subset." (PMID 31244833, 2019). "Among these genes are TGFβ1, IL10, and MYD88 which are known to participate in cardiac disease." (PMID 36248879, 2022). "In CD, IFN-γ, IL-2, IL-6, IL-10, IL-12, and IL-17 are proposed as surrogate markers of cardiac disease (versus no disease) (9, –, 14)." (PMID 34479416, 2021). "Other cytokines (TNF-alpha, IL-4, IL-17, IFN-gamma, CCL2, and IL-10) have shown differences between severe chagasic heart disease and the undetermined stage but not between the different stages of chagasic heart disease progression." (PMID 32455143, 2020). "Similarly, the IL10 SNPs rs1800890 (-3575 T>A), rs1800896 (-1082 G>A), and rs1800871 (-819 C>T) did not act as a genetic modifier of Chagas' heart disease outcome." (PMID 29768622, 2018). "Neither TGFB rs8179181, rs8105161, rs1800469), IL10 (rs1800890/rs1800896/rs1800871), nor TNF-BAT1-LTA (rs1800629/rs3853601/rs909253/rs2239704) analysed haplotypes displayed significant associations with Chagas' heart disease outcome." (PMID 29768622, 2018).
adenocarcinoma (20 papers, 2007 to 2025). A common cancer characterized by the presence of malignant glandular cells. "Elevated levels of IL-10 may be useful as diagnostic biomarkers for this adenocarcinoma." (PMID 36009467, 2022). "E. faecalis has been reported to induce IBD, which even progresses to rectal dysplasia and adenocarcinoma in the IL-10 knockout mice." (PMID 41476955, 2025). "We have previously shown that lumen filling tumors arise in IL-10−/− mice, which closely resemble human adenocarcinomas histologically." (PMID 21799775, 2011). "In IL-10−/− mice, at an average age of 15 weeks upcoming dysplasias progressed to infiltrating adenocarcinomas in a total of four animals (out of eight animals observed as described in “methods”)." (PMID 21799775, 2011). "In our study, IL-10 was detected in most of adenocarcinoma lesions; however, we were unable to rely IL-10 expression to leucocyte–endothelial interactions, as functional approaches like intravital microscopy cannot be applied to patients." (PMID 17325703, 2007). "Interestingly, the PD-L1 expression on adenocarcinomas-conditioned moDCs positively correlated with the phagocyte activity, IL-6 production, and IL-10 producing CD4+CD25+ T cell activation." (PMID 36194602, 2022). "Additionally, HT29 had a significantly lower capacity to induce IL-10 production by CD4+CD25+ lymphocytes than the HeLa adenocarcinoma cell line." (PMID 36194602, 2022). "However, we found that adenocarcinomas-educated moDCs’ IL-6 production positively correlates with IL-10 producing T cell activator capacity by monocyte-derived cells." (PMID 36194602, 2022). "It has been described that at six months of age, 60% of IL-10−/−-mice develop adenocarcinomas." (PMID 21799775, 2011). "We measured the concentration of IL-6, IL-10, TNF-α, MCP-1, INF-γ, and IL-12p70 secreted in the conditioned medium (CM) by the murine colon C-26 adenocarcinoma cells." (PMID 24967341, 2014). "Both effusion and blood IL-10 levels are notablely higher in non-adenocarcinoma patients compared to adenocarcinoma patients." (PMID 39003443, 2024). "The unstimulated group had low levels of TNFα and IL10, however, upon stimulation, we saw an additional in vitro release of TNFα and IL10 in both groups, but the release was not different in samples of patients with adenocarcinoma." (PMID 37610509, 2023). "IL-2 and IL-10 increased in mice that received untreated A549 cells, suggesting that the immune system mounts a regulated response against adenocarcinoma, which did not occur with A549NED cells." (PMID 36674504, 2023).
psychiatric disorder (19 papers, 2008 to 2025). A disorder characterized by behavioral and/or psychological abnormalities, often accompanied by physical symptoms. "Interleukin-10 (IL-10) is an anti-inflammatory cytokine which plays an important role in the regulation of neuronal function under pathophysiological conditions associated with elevated neuro-inflammatory response for different neurodegenerative and psychiatric disorders." (PMID 31324059, 2019). "It has been suggested that dysregulation of cytokines, particularly IL-1-β, IL-6, IL-10, interferon (IFN-γ), and TNF-α, contributes to the pathogenesis of certain psychiatric disorders." (PMID 37644934, 2023). "Antidepressants are hypothesized to treat mental illness via immunoregulatory pathways, by decreasing levels of pro-inflammatory cytokines such as TNF52, IL-6, IL-1β, and IL-10." (PMID 39941688, 2025). "However, some studies have displayed a similar negative correlation of the disease duration with IL-10 in the sera of patients with psychiatric disorders and with immune cell infiltrates in the temporal lobe parenchyma of refractory TLE + HS patients." (PMID 32532251, 2020).
respiratory diseases (19 papers, 2011 to 2025). "Recently, an IL10 polymorphism (rs1800872) was associated with NSAID-exacerbated respiratory disease in a Mexican mestizo population." (PMID 35456412, 2022). "We found that T CD4+/IL-4+ and T CD4+/IL-10+ populations were highly increased in the RS group, and our results are consistent with these reports, suggesting that chronic stress might be promoting lung susceptibility to infectious and respiratory diseases." (PMID 41155294, 2025). "In the promotor region of the IL10 gene, there are three SNPs, rs1800896, rs1800871 and rs1800872, associated with the onset, severity, progression and/or outcome of various diseases including autoimmune, allergic, neoplastic, gastrointestinal and respiratory diseases." (PMID 37600000, 2023). "Five individual mediators were different among the cohorts (MCP‐1, IL‐7, IL‐10, IL‐13, and IL‐15) with lower concentrations in the groups with respiratory disease, particularly COPD and CRS." (PMID 36780897, 2023). "(2007) have observed that upper-respiratory disease-prone athletes have lower serum resting IL-8, IL-10 e IL-1ra concentrations, culminating in impaired inflammatory regulation." (PMID 36685603, 2022). "Among them, representative respiratory diseases-related targets included IL-6, IL-10, IL-1β, TNF-α, interferon (IFN)-γ, epidermal growth factor (EGF) and its receptor (EGFR), TNF-α, transforming growth factor (TGF)-β1, etc." (PMID 31530860, 2019). "Based on these results and other findings in the literature, we suggest that the suppression of critical immunomodulatory cytokines, especially those that are anti‐inflammatory such as IL‐10, could be explored in future studies as potential nasal mucosal biomarkers of respiratory disease." (PMID 36780897, 2023).
retinopathy (11 papers, 2008 to 2023). "Such restoration of growth as well as pro/anti-inflammatory factors, such as VEGF, IL-1, and IL-10, is reported to decrease the occurrence of retinopathy." (PMID 33553187, 2021). "Admission plasma levels of TNF, interleukin-10, and soluble intercellular adhesion molecule (sICAM-1) were measured by ELISA in 135 retinopathy-positive CM cases." (PMID 27311750, 2016). "In summary, IL-10 promotes retinal neovascularization in a mouse model of oxygen-induced retinopathy." (PMID 18852882, 2008). "To determine if retinal macrophages from wild-type and IL-10−/− mice were exhibiting differential angiogenic phenotypes, we examined the gene expression profiles of in vivo derived retinal macrophages following oxygen-induced retinopathy." (PMID 18852882, 2008). "They decreased the expression of IL-6 and TNF-α and the production of iNOS, while anti-inflammatory IL-10 was upregulated both in hypoxia-treated BV2 cells and a retinopathy mouse model through inhibition of the NF-κB pathway." (PMID 36768783, 2023). "Interestingly, all of the genes that were upregulated in macrophages following oxygen-induced retinopathy were found to be 1) significantly upregulated in C57BL/6 macrophages and not in IL-10 deficient macrophages, 2) proangiogenic, and 3) cross regulative." (PMID 18852882, 2008). "IL-2, IL-10, IL-12, IFN-α, and TNF-α were unmeasurable in significantly more diabetic samples, and where measurable, the median levels were significantly lower in diabetic patients with and without retinopathy compared to non-diabetics." (PMID 22511846, 2012).
peripheral neuropathy (10 papers, 2017 to 2025). A disorder affecting the peripheral nervous system. "Paclitaxel-treated animals show the attenuation of peripheral neuropathy by the anti-inflammatory thalidomide, minocycline or the anti-inflammatory cytokine IL10." (PMID 28182729, 2017). "Furthermore, paclitaxel-exposed T cells stimulate macrophages to secrete interleukin-10 (IL-10) via interleukin-13 (IL-13), and macrophage-derived IL-10 engages IL-10 receptors (IL-10R) on DRGs to counteract paclitaxel-induced peripheral neuropathy." (PMID 41229440, 2025). "Resolution of chemotherapy-induced peripheral neuropathy (CIPN) after treatment completion depends on CD8+ T cells and on IL-10 produced by other cells." (PMID 35260535, 2022). "One study showed that high-dose vitamin D3 supplementation of 40,000 IU/week (~5700 IU/d) for 24 weeks was associated with improvement in clinical manifestation, cutaneous microcirculation and inflammatory markers (decreased IL-6 and increased IL-10) in patients with T2DM and peripheral neuropathy." (PMID 36558465, 2022).
benign tumors (5 papers, 2015 to 2023). "IL-10 is a potent anti-inflammatory cytokine as well as a cardio-protective factor in the ischemic heart." (PMID 31196181, 2019). "Of these, 15 proteins (PRSS8, MK, WFDC2 (HE4), IL-10, SOD2, PARP-1, hK11, PVRL4, MUC-16 (CA125), FR-alpha, CDH3, NTRK3, IL-8, IL-17C, EN-RAGE) were selected from the comparison between OC stage I–IV and benign tumors." (PMID 30519148, 2018).
gastrointestinal disease (5 papers, 2010 to 2023). A disease that occurs in the gastrointestinal system, excluding the hepatobiliary system. "IL-6 maintains homeostasis by stimulating the proliferation and triggering an increase in neutrophil count, and IL-10 has been found to be negatively correlated with the occurrence and progression of gastrointestinal disease." (PMID 37819128, 2023). "Cytokine-mediated dysfunction of tight junctions is important in gastrointestinal disease as cytokines and other growth factors may act to alternatively decrease (e.g., IL-10) or increase (e.g., IL-6) gut permeability." (PMID 30669283, 2019).
brain disease (4 papers, 2018 to 2020). "In this context, several recent studies have implicated microglia and defective IL10 signaling in various brain disease and lesion models." (PMID 33391287, 2020). "IL-10 has an important anti-inflammatory action, and its upregulated expression is beneficial to the neuroplastic niche in brain disease." (PMID 33488693, 2020). "While it is clear that glia can be a significant source of IL-10, IL-19 and perhaps IL-20 and IL-24, and these resident CNS cells are responsive to their actions, the functions of the IL-10 cytokine family in health and brain disorders have been understudied." (PMID 30542269, 2018).
CNS tumors (4 papers, 2013 to 2023). "In non-CNS tumors, IL-10 has been shown to augment CD8+ T-cell cytotoxicity in a manner that is dependent on its expression of IFN-γ and granzymes." (PMID 26217588, 2015). "We have explored the value of CSF interleukin (IL)-10 in PCNSL and found that CSF IL-10 ≥ 8.2 pg/ml can differentiate PCNSL well from other CNS tumors, with sensitivity and specialty of 95.5% and 96.1%, respectively." (PMID 36644235, 2023).
gastrointestinal disorders (4 papers, 2023 to 2026). "Immunomodulation:- ↓ IL6 and ↑ IL-10.Management of gastrointestinal disorders:- Most efficient treatment efficacy by producing the quickest therapeutic effect.- No recurrence of IBD at least for 6 months after the experiment." (PMID 37954670, 2023).
hematological cancer (3 papers, 2019 to 2022). "A meta-analysis of 21 studies also revealed that high IL-10 levels were associated with worse disease-free and overall survival in both solid and hematological cancer patients." (PMID 31448052, 2019). "The serum concentration of IL–10 has been found to be higher in patients with NHL, which may lead to decreased cell mediated immunity resulting in activation of latent TB Hematopoietic cancer was related to TB disease developing." (PMID 32986373, 2020).
neurodevelopmental disorder (3 papers, 2020 to 2025). A behavioral and cognitive disorder with onset during the developmental period that involves impaired or aberrant development of intellectual, motor, or social functions. "IL‐10 is well known for its role in suppressing neuroinflammation, a process implicated in ASD and related neurodevelopmental disorders." (PMID 40827476, 2025). "The selected cytokines comprised IL-1β, IL-6, IL-10, TNF-α, and IFN-γ, which have not only been found dysregulated in the MIA paradigm, but also form part of the inflammatory profiles in the neurodevelopmental disorders reflected in the MIA model (eg)." (PMID 39033141, 2024).
systemic renal diseases (2 papers, 2023 to 2024). "Bregs are important in kidney transplant recipients due to their suppressive function, potential tolerance-inducing power through both IL-10-dependent and IL-10-independent mechanisms, and potential protective role in systemic renal diseases such as graft acceptance and reducing DSA production." (PMID 38892795, 2024). "Our study confirms a significant increase in the expression of the receptor for IL-10 under the influence of ash leaf preparations, which may imply the advisability of using the raw material in the treatment of urinary tract disorders." (PMID 36835169, 2023).
eye disorder (1 paper, 2023). A non-neoplastic or neoplastic disorder that affects the eye. "Consequently, an increased understanding of the role of IL-10 in the POAG eye disorder may open the door to future treatments." (PMID 37511830, 2023).